MIR362 (microRNA 362)
Synonyms: hsa-mir-362; MIRN362; mir-362
Gene: MicroRNA gene on chromosome X (50,008,964 to 50,009,028, forward strand). Ensembl gene ENSG00000208015.
Gene Ontology:
Biological process: miRNA-mediated post-transcriptional gene silencing
Cellular component: RISC complex
Homologues: Orthologues: chimpanzee ptr-mir-362 (100% identical).